ADPGK (ADP dependent glucokinase)
Description:
Catalyzes the phosphorylation of D-glucose to D-glucose 6-phosphate using ADP as the phosphate donor. GDP and CDP can replace ADP, but with reduced efficiency.
Synonyms: ADP-GK; DKFZp434B195; 2610017G09Rik
Tractability: Antibody: UniProt places it where antibodies can reach, with high confidence; UniProt predicts a signal peptide or a membrane-spanning region; its Gene Ontology location is reachable by antibodies, with medium confidence. PROTAC: ubiquitination databases record sites on it; its protein half-life has been measured.
Gene: Protein-coding gene on chromosome 15 (72,751,294 to 72,785,846, reverse strand). Ensembl gene ENSG00000159322.
Subcellular location: Secreted
Subcellular location (Human Protein Atlas): Centrosome
Pathways (Reactome):
Metabolism: Glycolysis
Gene Ontology:
Molecular function: ADP-specific glucokinase activity; phosphotransferase activity, alcohol group as acceptor
Biological process: glucose metabolic process; glycolytic process through glucose-6-phosphate; carbohydrate metabolic process; glycolytic process
Cellular component: endoplasmic reticulum; membrane; endoplasmic reticulum membrane; extracellular region
Genetic constraint (gnomAD): Loss-of-function variants: 27 observed, 39.74 expected, observed/expected ratio (o/e) 0.68, 90% interval 0.5 to 0.94. The upper end of that interval is the gene's LOEUF score, 0.94, which puts it in group 3 of 6, group 1 being the genes least tolerant of losing a copy. Missense variants: 560 observed, 593.31 expected, observed/expected ratio (o/e) 0.94, 90% interval 0.88 to 1.01. Synonymous variants: 263 observed, 239.94 expected, observed/expected ratio (o/e) 1.1, 90% interval 0.99 to 1.21.
Homologues: Orthologues: chimpanzee ADPGK (100% identical), macaque ADPGK (99% identical), pig ADPGK (93% identical), dog ADPGK (93% identical), rat Adpgk (92% identical), mouse Adpgk (91% identical), guinea pig ADPGK (89% identical), rabbit ADPGK (79% identical), zebrafish adpgk (63% identical), tropical clawed frog adpgkl (62% identical), Caenorhabditis elegans C50D2.7 (34% identical).
Diseases named in the same sentence as ADPGK in open-access papers:
ADPGK is named in the same sentence as 24 diseases in open-access papers, as found by Europe PMC text mining. Sharing a sentence is not in itself a finding about the gene and the disease. The quoted sentences say what the papers report.
prostate carcinoma (3 papers, 2023 to 2025). A carcinoma that arises from epithelial cells of the prostate gland. "ADPGK can accelerate prostate cancer glycolysis and progression through activation of ALDOC-AMPK signaling." (PMID 38590647, 2024). "This suggests that ADPGK could be an effective target and marker for prostate cancer treatment and prognosis assessment." (PMID 38590647, 2024). "In addition, their experiments demonstrated that ADPGK could promote glycolysis in prostate cancer cells through activation of the ALDOC-AMPK pathway." (PMID 41035662, 2025).
breast carcinoma (2 papers, 2019 to 2024). "SK2 KD universally downregulated expression of CAPZA1 (inhibition of autophagy and EMT) and also decreased expression of NSUN3, ADPGK and KLHDC10 in prostate and ITGAV in breast cancer cell lines." (PMID 30971929, 2019).
energy metabolic disorder (2 papers, 2023 to 2024). "After ADPGK knockout, Jurkat T cells exhibited severe energy metabolic disorder, impeding the Warburg effect." (PMID 38082365, 2023).
lung carcinoma (2 papers, 2020 to 2025). "Furthermore, LCP1, ADPGK, and LCP1+ADPGK successfully predicted pneumonitis in 26 lung cancer patients with AUC as 0.74, 0.76, and 0.77, respectively, suggesting the potential utility of LCP1 and ADPGK in predicting a specific type of irAE in a specific cancer." (PMID 33009409, 2020).
melanoma (2 papers, 2023). A malignant, usually aggressive tumor composed of atypical, neoplastic melanocytes. "Subcutaneous injection of EVs carrying ovalbumin or ADPGK mRNA in mice significantly arrested the progression of melanoma." (PMID 37514088, 2023). "The vaccine incorporates new antigens from ADPGK in MC-38 tumors and M16 and M10 in B27F30 melanoma tumors into EVs." (PMID 37514088, 2023).
prostate adenocarcinoma (2 papers, 2023 to 2025). "ADP-dependent glucokinase (ADPGK) is overexpressed in prostate adenocarcinoma and has been shown to promote PCa cell proliferation and migration in vitro and in vivo, while predicting poor prognosis of patients." (PMID 41281744, 2025). "ADPGK was the only glucokinase that was both upregulated and predicted worse overall survival (OS) in prostate adenocarcinoma (PRAD)." (PMID 38082365, 2023).
Arterial thrombosis (1 paper, 2025). The formation of a blood clot inside an artery. "ADPGK acts as an inhibitor of pyruvate dehydrogenase kinase and can inhibit platelet aggregation and arterial thrombosis." (PMID 40727388, 2025).
benign prostate hyperplasia (1 paper, 2023). "In addition, by performing an IHC assay, the team has observed that ADPGK expression was also higher in PCa tissues than in benign prostate hyperplasia (BPH) tissues." (PMID 38082365, 2023).
Burkitt lymphoma (1 paper, 2020). A rare form of malignant mature B-cell non-Hodgkin lymphoma. "Ramos WT exhibited migration rates more than double compared to its KO counterparts, indicating a significant loss in chemotactic attraction capabilities of Burkitt’s lymphoma cells upon removal of ADPGK." (PMID 32788680, 2020). "The effects amplified greatly upon stimulation-based proliferation, thus providing a novel Burkitt’s lymphoma targeting mechanism originating from metabolic catastrophe induced in the cells by removal of ADPGK." (PMID 32788680, 2020). "In this study, we present ADP-dependent glucokinase (ADPGK) as a novel glucose sensor and a potential onco-target in specifically high-proliferating cells in Burkitt’s lymphoma (BL)." (PMID 32788680, 2020).
hypothyroidism (1 paper, 2025). Abnormally low levels of thyroid hormone. "For example, genetically predicted plasma levels of ALDH2, BCL2L15, WASL, POLR2F, and ADPGK were positively associated with hypothyroidism risk, while H2BC21 and H2BC26 showed negative associations." (PMID 40868097, 2025).
lymphoma (1 paper, 2020). A malignant (clonal) proliferation of B- lymphocytes or T- lymphocytes which involves the lymph nodes, bone marrow and/or extranodal sites. "PMA activated THP-1 monocytes were co-cultured with stimulated Ramos WT or ADPGK KO cells for a period of 48 h, which corresponds to the activation state of B-cells signifying high proliferation and high glycolytic activity found in aggressively growing lymphomas." (PMID 32788680, 2020). "To monitor the development of lymphoma xenografts in zebrafish larvae over a period of two days, we injected PMA activated Ramos WT and ADPGK KO cells in the yolk of kdrl:GFP zebrafish larvae 48 hours post fertilization (hpf)." (PMID 32788680, 2020). "Nonetheless, the higher residual expression of CD20 in ADPGK KO cells is important in the light of using chemotherapeutics such as Rituximab53 which depend on binding to CD20 and might also prove useful in lymphomas exhibiting resistance to this drug via shedding off the drug-CD20 complex." (PMID 32788680, 2020).
rectum adenocarcinoma (1 paper, 2023). An adenocarcinoma arising from the rectum. "Next, by performing pan-cancer analysis, high expression of ADPGK was observed in PRAD and other cancer types, such as uterine corpus endometrial carcinoma (UCEC), stomach adenocarcinoma (STAD), and rectum adenocarcinoma (READ)." (PMID 38082365, 2023).
tumor (14 papers, 2013 to 2025). "In this study we use a pair of ZFNs, custom-designed to target a genomically unique sequence in the ADPGK gene, to generate human tumour cell lines with frameshift mutations at the target site and which completely lack ADPGK protein by immunoblotting." (PMID 23799003, 2013). "It was discovered that the ADPGK knockout Ramos BL cells showed attenuated tumour aggressiveness in vitro and in vivo." (PMID 38590647, 2024). "Currently, ADPGK exhibits high expression in hormone-dependent breast and prostate tumours, promoting the uptake of glucose via glycolysis to stimulate tumour proliferation, migration, and invasion." (PMID 38590647, 2024). "It should also be noted that ADPGK can enhance tumour cell survival under highly glycolysis-dependent conditions." (PMID 38590647, 2024). "This revealed a wide array of unique rearrangements in each mouse assayed, suggesting that many different T cells were being activated by ADPGK-loaded cDC1s and infiltrating the tumor." (PMID 37917174, 2024). "Immunofluorescence assays of subcutaneous tumor tissues revealed that ADPGK was also significantly upregulated in the ADPGK OE group." (PMID 38082365, 2023). "Specifically, a study in T cells revealed that ADPGK can enhance the Warburg effect in T cells, but the specific mechanism of ADPGK in tumor cells is still unclear." (PMID 38082365, 2023). "The (PDT + CTLA-4)-gel multi laser treatment also induced more tumor neo-antigen (ADPGK and RPL18)-specific CD8+ T cells than the control group." (PMID 35974207, 2022). "The findings were further cemented by in vitro measures of tumour aggressiveness via migration and co-culture, showing a reduced capability of ADPGK KO cells to transform tissue resident macrophages for their advantage." (PMID 32788680, 2020). "The geometric mean of LCP1 and ADPGK was also higher in pre-treatment tumor samples of patients with irAEs (P value = 0.005)." (PMID 33009409, 2020). "We found reduced tumour aggressiveness upon activation, both in vitro and in vivo zebrafish, and a hindered activation mediated differentiation of ADPGK KO cells." (PMID 32788680, 2020). "We now report ADPGK knock-out Ramos BL cells display abated in vitro and in vivo tumour aggressiveness, via tumour-macrophage co-culture, migration and Zebrafish xenograft studies." (PMID 32788680, 2020). "Given the importance of glucose phosphorylation in tumour metabolism, we focus here on the role of ADPGK in human tumour cell lines." (PMID 23799003, 2013). "Here we use ZFNs to interrogate the biological function of ADPGK, which encodes an ADP-dependent glucokinase (ADPGK), in human tumour cell lines." (PMID 23799003, 2013). "The intriguing observation of a clear effect of ADPGK on survival of H460 cells under certain stress conditions in vitro indicates that a deeper understanding of its role in tumour cell biology is needed." (PMID 23799003, 2013). "Western blots from fresh frozen samples of each tumour that reached the endpoint size showed a reduction of the 54-kDa ADPGK band in most of the ADPGK knockout tumours, but a residual band of varying intensity was evident." (PMID 23799003, 2013). "Due to the high degree of heterogeneity between different tumours, it is uncertain whether these two contradictory conclusions apply to ccRCC and whether ADPGK can adjust glycolysis in ccRCC cells." (PMID 41035662, 2025). "The peptide from ADPGK shows potential as a tumour neoantigen in such immunotherapy." (PMID 38590647, 2024). "A negative correlation between ADPGK and tumor mutation burden in PCa was also observed, albeit the coefficients are small." (PMID 38082365, 2023). "However, due to limited research, the biological behavior and mechanisms of ADPGK in tumor cells are still unclear." (PMID 38082365, 2023).
tumor (continued). "Collectively, the results demonstrate that ADPGK can contribute to tumour cell survival under conditions of high glycolytic dependence, but the phenotype resulting from knockout of ADPGK is cell line dependent and appears to be unrelated to priming of glycolysis in these lines." (PMID 23799003, 2013). "Given the important role of hypoxia as a driver of tumour angiogenesis, we sought to determine whether the reduced survival of H460 ADPGK knockouts under anoxia in vitro translates into compromised growth as tumour xenografts." (PMID 23799003, 2013). "This presumably reflects a variable murine stromal component, given that the antibody also recognised murine ADPGK in mouse liver samples; this is consistent with the presence of a cross-reactive 25 kDa band in mouse liver and in the ADPGK knockout tumour samples with the most intense 54 kDa bands." (PMID 23799003, 2013). "The results revealed that the tumor volume of the ADPGK OE group was significantly larger than that of the control group, and the growth curve revealed that ADPGK overexpression could significantly promote the growth of xenografts, with a significant difference (P = 0.0252)." (PMID 38082365, 2023). "Hence, we hypothesized that knock-out of ADPGK from Ramos BL cells will induce a metabolic catastrophe in these cells, affecting the tumour aggressiveness of these cells in vitro and in vivo in zebrafish model." (PMID 32788680, 2020). "The recent demonstration of the diversion of glycolytic flux by ADPGK to hyper-reduce ubiquinone and drive mitochondrial generation of ROS, in response to T-cell receptor signaling, also raises the possibility that ADPGK might contribute to elevated ROS production in some tumour cells." (PMID 23799003, 2013). "Seven GRPGs (PIM2, PGK1, ADPGK, YWHAZ, PTK2, PGAM1, and VDAC1) were significantly upregulated in the TCGA-BRCA tumor tissues." (PMID 40046063, 2025). "The mRNA expression of these genes in TCGA-PRAD samples was determined, and in both non-paired and paired samples, HK2, HK3 and ADPGK were overexpressed, while GCK and HK1 were downregulated in tumor samples compared with normal tissues." (PMID 38082365, 2023). "In addition, GSE29044 had more differentially expressed GRPGs between normal and tumor tissues (CS, PGK1, HNRNPA1, ADPGK, YWHAZ, PTK2, and PGAM1) than GSE42568 (CS, HNRNPA1, ADPGK, and PTK2)." (PMID 40046063, 2025). "This indicates that although ADPGK is highly expressed in human tumour cell lines, it does not appear to contribute significantly to glycolysis." (PMID 38590647, 2024). "We collected tumor-infiltrating T cells from these mice and assessed whether any of the CD8+ T cells in these tumors were specific for ADPGK neoantigen." (PMID 37917174, 2024). "Overexpression of ADPGK in H460 and HCT116 human tumour cells did not lead to cell proliferation or glycolysis, and inhibition of ADPGK by siRNA did not result in the inhibition of glycolysis or cell death due to hypoxia." (PMID 38590647, 2024). "Among the six metabolic genes, ADPGK is an ADP-dependent glucokinase and catalyzes ADP-dependent phosphorylation of glucose, which is involved in gluconeogenesis/glycolysis in cancer progression and is upregulated in HCC tumor tissues." (PMID 36250026, 2022). "Additionally, the database indicates high expression of ADPGK in tumours and differential expression in comparison to normal tissues." (PMID 38590647, 2024). "ADPGK is highly expressed in immune cells of both myeloid and lymphoid lineages and use of ADP instead of ATP by the enzyme for priming glucose hints at its role in nutrient deprived and hypoxic conditions, such as those prevalent in tumour growth, where ATP is available in lean amounts." (PMID 32788680, 2020). "Thus ADPGK does not appear to participate in an analogous signalling pathway in HCT116 or H460 tumour cells under the conditions we have tested." (PMID 23799003, 2013).
tumor (continued). "Our results suggest that ADPGK may not be a useful target for cancer therapy, although it needs to be born in mind that the current investigation explores just two clones from each of two human tumour cell lines." (PMID 23799003, 2013). "ADPGK knockout had no discernible effect on growth of the H460 or HCT116 clones, and steady state hypoxic fractions were unaffected in the resulting tumours." (PMID 23799003, 2013). "Thus moderate levels of hypoxia in tumours, sufficient to induce HIF-1 stabilisation and angiogenesis, do not appear to result in ADPGK dependence." (PMID 23799003, 2013). "Our initial attempt to test this hypothesis examined the effect of suppressing ADPGK expression, with and without suppression of HK2, in HCT116 and H460 human tumour cell lines using RNA interference." (PMID 23799003, 2013).
cancer (9 papers, 2013 to 2025). A tumor composed of atypical neoplastic, often pleomorphic cells that invade other tissues. "Currently, the study demonstrates that ADPGK is linked to metabolic and nervous system diseases and has a close association with the development of malignant tumours." (PMID 38590647, 2024). "Among them AAAS, HK3, and ADPGK the expression of three genes was obviously raised in cancer samples and was significantly correlated with prognosis." (PMID 41035662, 2025). "We then validated the link between ADPGK and cancer cell invasion and metastasis by in vitro experiments on ccRCC cell lines." (PMID 41035662, 2025). "We identify driver mutations in ADPGK, NUP93, PCGF6, PKP2 and SLC22A5, which are verified to enhance cancer cell migration and prompt metastasis with in vitro experiments." (PMID 27625789, 2016). "All of the results suggest that MTs of ADPGK, PCGF6, PKP2, NUP93 and SLC22A5 can be the driver mutations controlling the cancer metastasis via affecting the EMT pathways where Snail, Claudin-1 or ZEB1 is involved." (PMID 27625789, 2016). "Additionally, lower content of PDI in ADPGK KO cells pointed towards a reduced proliferative phenotype of these cells as the protein exhibits a pro-survival/anti-apoptotic effect in cancer cells." (PMID 32788680, 2020). "We reassigned the 7 screened genes based on gene expression differences between cancer and paracancerous tissues, and applied an unsupervised consensus clustering algorithm to establish a typology based on the expression of glucose metabolism-related genes (ADPGK)." (PMID 41035662, 2025).
cardiovascular diseases (1 paper, 2025). "In another aspect, genetic susceptibility to higher levels of ALDH2, POLR2F, and ADPGK were associated with increased risks of various cardiovascular diseases." (PMID 40868097, 2025).
infection (1 paper, 2024). The state of being infected such as from the introduction of a foreign agent such as serum, vaccine, antigenic substance or organism. "By contrast, Mtb CDC1551 infection significantly upregulated the expression of selective markers of glycolysis (ADPGK and LDHA) and all tested TCA cycle and gluconeogenesis genes, compared to the uninfected controls." (PMID 38980014, 2024).
nervous system diseases (1 paper, 2024). "This study highlights the potential role that ADPGK seems to play in enhancing injury-induced macrophagocytosis by macrophages in vivo, making it a promising target for future therapies in neurological diseases." (PMID 38590647, 2024).
ADPGK also shares sentences with these, for which no sentence is quoted: clear cell renal cell carcinoma (1 paper); colon carcinoma (1); Obesity (1); periodontitis (1); pneumonitis (1); rectal cancer (1); uterine corpus endometrial carcinoma (1).